ENY2 (ENY2 transcription and export complex 2 subunit)
Description:
Involved in mRNA export coupled transcription activation by association with both the TREX-2 and the SAGA complexes. The transcription regulatory histone acetylation (HAT) complex SAGA is a multiprotein complex that activates transcription by remodeling chromatin and mediating histone acetylation and deubiquitination. Within the SAGA complex, participates in a subcomplex that specifically deubiquitinates both histones H2A and H2B. The SAGA complex is recruited to specific gene promoters by activators such as MYC, where it is required for transcription. Required for nuclear receptor-mediated transactivation. As a component of the TREX-2 complex, involved in the export of mRNAs to the cytoplasm through the nuclear pores.
Synonyms: DC6; FLJ20480; Sus1; e(y)2
Tractability: PROTAC: UniProt records ubiquitination sites on it; ubiquitination databases record sites on it; its protein half-life has been measured.
Gene: Protein-coding gene on chromosome 8 (109,334,324 to 109,345,954, forward strand). Ensembl gene ENSG00000120533.
Subcellular location: Nucleus, nucleoplasm
Subcellular location (Human Protein Atlas): Mitochondria; Nucleoplasm
Pathways (Reactome):
Chromatin organization: HATs acetylate histones
Gene Ontology:
Molecular function: protein binding; transcription coactivator activity; chromatin binding
Biological process: poly(A)+ mRNA export from nucleus; positive regulation of DNA-templated transcription; regulation of transcription by RNA polymerase II; mRNA export from nucleus; positive regulation of transcription by RNA polymerase II; regulation of DNA repair; regulation of RNA splicing; transcription elongation by RNA polymerase II
Cellular component: DUBm complex; nuclear pore nuclear basket; SAGA complex; transcription export complex 2; transcription factor TFTC complex; nuclear pore; nucleoplasm; nucleus; SAGA-type complex
Genetic constraint (gnomAD): Loss-of-function variants: 4 observed, 12.39 expected, observed/expected ratio (o/e) 0.32, 90% interval 0.16 to 0.74. The upper end of that interval is the gene's LOEUF score, 0.74, which puts it in group 3 of 6, group 1 being the genes least tolerant of losing a copy. Missense variants: 49 observed, 108.5 expected, observed/expected ratio (o/e) 0.45, 90% interval 0.36 to 0.57. Synonymous variants: 45 observed, 37.03 expected, observed/expected ratio (o/e) 1.22, 90% interval 0.96 to 1.56.
Homologues: Orthologues: dog ENY2 (100% identical), macaque ENY2 (100% identical), pig ENY2 (100% identical), rabbit ENY2 (100% identical), rat Eny2 (98% identical), guinea pig ENY2 (96% identical), mouse Eny2 (95% identical), tropical clawed frog eny2 (89% identical), zebrafish eny2 (80% identical), chimpanzee ENY2 (76% identical), Drosophila melanogaster e(y)2 (42% identical).
Diseases named in the same sentence as ENY2 in open-access papers:
ENY2 is named in the same sentence as 16 diseases in open-access papers, as found by Europe PMC text mining. Sharing a sentence is not in itself a finding about the gene and the disease. The quoted sentences say what the papers report.
breast carcinoma (2 papers, 2023 to 2024). "The upregulation of ENY-2 could also contribute to the development of resistant HER-2+ breast cancer cells, although the detailed mechanism is still unclear." (PMID 39769375, 2024). "Furthermore, ENY2 was found to facilitate breast cancer cell migration and metastasis both in vitro and in vivo." (PMID 39769375, 2024). "NUDCD1, ENY2, PNO1, CCT4 and PSMD14 are considered to promote the proliferation, invasion and treatment resistance of tumor cells in a variety of cancers, including pancreatic cancer, rectal cancer, liver cancer, breast cancer, glial cancer and head and neck squamous cell carcinoma." (PMID 37827692, 2023).
insulinoma (1 paper, 2012). "In this study we show that the knockdown of the protein Eny2 results in increased glucose and incretin-stimulated insulin secretion from at baseline poorly responsive INS-1E insulinoma cells." (PMID 22649445, 2012). "We next confirmed the expression of Eny2 mRNA in islets from C57Bl/6 mice using rtPCR and also in rat INS-1E insulinoma cells." (PMID 22649445, 2012).
osteosarcoma (1 paper, 2025). A usually aggressive malignant bone-forming mesenchymal neoplasm, predominantly affecting adolescents and young adults. "Meanwhile, higher expression levels of SMARCB1, UBQLN2, ENY2, and BAZ1B was observed in high-grade osteosarcoma prechemotherapy biopsy samples than that of MSCs." (PMID 40989695, 2025).
ovarian carcinoma (1 paper, 2022). A malignant neoplasm originating from the surface ovarian epithelium. "Moreover, ENY2, one of the mRNA transcription and export complex subunits, was also observed to have a higher frequency of copy number alterations (CNAs) and a higher mRNA expression level in ovarian cancer, indicating that ENY2 might act as a cancer driver gene." (PMID 35992857, 2022).
triple-negative breast carcinoma (1 paper, 2022). An invasive breast carcinoma which is negative for expression of estrogen receptor (ER), progesterone receptor (PR), and human epidermal growth factor receptor 2 (HER2). "Notably, ENY2 was identified as a prognostic signature for lung metastasis in triple-negative breast cancer." (PMID 35992857, 2022).
tumor (7 papers, 2020 to 2026). "For example, ATXN7L3 and ENY2 stimulate activity of multiple H2B deubiquitinases that play a key role in cellular proliferation and tumor growth." (PMID 31737900, 2020). "ENY2, a nuclear transcription factor, coordinates the activity of multiple H2B deubiquitinases, thereby potentiating tumor proliferation and growth." (PMID 33221751, 2020). "In accordance with this finding, ENY2 was important for cellular proliferation and tumor growth." (PMID 35992857, 2022). "Similarly, the RNA modification-related genes DHX35, DHX8, ENY2, and FTSJ1 also upregulated in most tumor tissues." (PMID 40041484, 2025). "Moreover, ENY2 and GPAA1 were expressed in multiple cell types including CAF, TEC, TAM, and/or tumor cells." (PMID 35992857, 2022).
cancer (6 papers, 2017 to 2026). A tumor composed of atypical neoplastic, often pleomorphic cells that invade other tissues. "ENY2 transcription and export complex 2 subunit (ENY2) is a transcription-associated nuclear protein that is upregulated in several cancers." (PMID 41642454, 2026). "Other TREX-2 components like ENY-2, which is associated with deubiquitination machinery, are also markedly elevated in many types of cancers including hepatocellular carcinoma and ovarian cancer." (PMID 39769375, 2024). "Interestingly, amongst those genes we found Eny2, which is a transcription factor, whose misregulation has been speculated to be linked to cancer and neurodegenerative diseases." (PMID 34614020, 2021). "The deregulation of mRNA export by ENY-2 and cell cycle disruption is a key to the development of cancers." (PMID 39769375, 2024). "The functional analysis of the genes correlated with ENY2 revealed that ENY2 might be involved in telomere maintenance, one of the fundamental hallmarks of cancer." (PMID 35992857, 2022).
ENY2 also shares sentences with these, for which no sentence is quoted: infection (4 papers); malaria (2); gastric cancer (1); head and neck squamous cell carcinoma (1); hepatocellular carcinoma (1); liver cancer (1); neurodegenerative disease (1); pancreatic cancer (1); rectal cancer (1).